STX2 (syntaxin 2)
Diseases named in the same sentence as STX2 in open-access papers (continued):
Sharing a sentence is not in itself a finding about the gene and the disease.
infection (continued). "After infecting the strains with the Stx2 phage Min27, progeny phage titer in the hns-deleted strain harboring the Min27 phage-derived spacer showed a nearly 100-fold decrease in comparison to the other strains, 12 h post-infection." (PMID 28458663, 2017). "No lytic infection of the commensal E. coli isolates was observed which is consistent with the low rate of lytic infection by Stx2-encoding phages observed in other studies." (PMID 25692100, 2015). "While all transcytosis studies on polarized Gb3-negative human T84 colon carcinoma cells have been performed with purified Stx1, we have studied Stx production, release and translocation during infection with Stx2-producing STEC O157:H7 and O104:H4 bacterial strains." (PMID 24612002, 2014). "In addition, Stx2 translocation during MA EDL933 infection was significantly increased compared with purified Stx2 alone indicating a role of the bacterial infection process in Stx absorption." (PMID 24612002, 2014). "However, in contrast to Stx2, Stx1 was detected intracellularly and represented only 2–4% of total Stx released during infection." (PMID 24612002, 2014). "Nevertheless we could observe that such strains induced CPE onto Vero cells monolayers after the infection with the stx2-phages." (PMID 24999453, 2014). "Secondly, the large numbers of inflammatory cells (macrophages and/or neutrophils) present during the infection process may release biologically active Stx2 close to target endothelial cells." (PMID 23451160, 2013). "Anti-Stx-2 IgY protected mice from death caused by GPU993-S infection, but anti-Stx-1 IgY did not affect mortality." (PMID 22028896, 2011). "Therefore, in this work we analyzed the hypothesis that human cell lines participate in Stx2 production after infection with EHEC strains." (PMID 31947665, 2020). "However, in 5–7% of infected persons, the infection leads to a systemic, sometimes life-threatening complication known as HUS, a development which is mediated by the bacterial expression of Shiga toxins, Stx1 and Stx2, encoded by the stx1 and stx2 genes." (PMID 32572054, 2020). "In addition, Stx2 translocation via dynamin and macropinocytic pathways was also significantly decreased, showing that both mechanisms also may play a role on Stx2 transcytosis during O157:H7Δstx2 infection." (PMID 31824869, 2019). "The results of this study demonstrate that the humanized anti-Stx2 monoclonal antibody TMA-15 is highly protective against neuropathological sequelae of EHEC infection in the neonatal gnotobiotic piglet model when administered within 24 h after the onset of infection." (PMID 28134751, 2017). "Hence, the ability of TF-1 and WA-8 to protect HeLa cells against the infection with Stx2 was speculated to be due to the neutralizing effect of the peptides." (PMID 26903273, 2016). "Since there is a positive correlation between Stx2 expression by EHEC and a greater risk of HUS developing as a consequence of infection, we postulated that there may be risk-related signals in the cytokine/chemokine response profile of macrophages exposed to Stx1 or Stx2." (PMID 26473922, 2015). "In a mouse model of Stx1/2-positive EDL933 infection-induced HUS, the presence of Stx2-positive monocytes in peripheral blood and infiltrated kidney tissues was observed." (PMID 39871175, 2025). "Employing the EDL933 infection-induced mouse HUS model, we observed a significant number of Stx2-positive monocytes in both peripheral blood and kidney tissues." (PMID 39871175, 2025). "Specifically, we employed the LPS/Stx2-induced murine HUS model and the Stx1/2-positive EDL933 infection-induced murine HUS model." (PMID 39871175, 2025). "The Stx2 is more clinically important than Stx1, as Stx2 infection has a higher probability of HUS development compared to either Stx1 or both Stx1 and Stx2." (PMID 38921792, 2024).
infection (continued). "The infection of macrophages with norV+ EHEC strains reduces the NO concentration and leads to a higher level of Stx2 than within macrophages infected with norV mutants." (PMID 32825770, 2020). "Quantification of apical Stx2 levels after EDL933 and H1121 infection by ELISA and VCCA yielded comparable results." (PMID 24612002, 2014). "The finding that O157:H7Δstx2 infection significantly increased Stx2 cytotoxicity in HCT-8 cells led the studies to determine which pathways are involved in Stx2 uptake and cytotoxicity and, in turn, which ones were stimulated by O157:H7Δstx2 infection." (PMID 31824869, 2019). "In this study, we found that dynamin-dependent Stx2 endocytosis had no relevance on Stx2 uptake or cytotoxic effects when O157:H7Δstx2 was absent but did significantly contribute to Stx2 cytotoxicity upon O157:H7Δstx2 infection." (PMID 31824869, 2019). "We observed that the stx2-phages used in this study seem not to have specificity for particular E. coli groups although the efficacy of the infections varied with the phage used." (PMID 24999453, 2014). "The authors observed that none of the bacterial strains tested showed evidences of infection with the stx2-phage in spite of the high titer used." (PMID 24999453, 2014). "Although immune cells may produce low doses of Stx2, they may play an important role in the EHEC pathogenesis and in the global course of infection." (PMID 23451160, 2013). "In the same study, we also reported that a similar infection with a derivative of EDL933 isogenic except for a deletion of the stx2 genes does not result in any of the pathogical changes seen with the wild-type parent strain." (PMID 23555250, 2013). "As the Stx2 phage can be induced during infection leading to a much higher level of stx2 expression, we used mitomycin C, a stimulus of the SOS response, for induction to determine levels of induced stx2 expression in vitro." (PMID 22558360, 2012). "Expression of stx2 at 24 h post infection could not be quantified for either strain as the number of transcripts was below the level of detection." (PMID 35056555, 2022). "Stool from mice infected with the most virulent strains that produced only Stx2 was ~10- to 100-fold more cytotoxic than from avirulent strain JH2012 on days 1 and 3 post-infection and 10-fold more cytotoxic than from the strain with delayed virulence, JH2013, on day 1 post-infection." (PMID 32175286, 2020). "However, the observed resistance of HNCMB 20080 to infection with Stx2-carrying phages and its derivates, does not support this possibility." (PMID 33488558, 2020). "Further, C. rodentium (Φstx2dact) mutants that do not respond to DNA damage or express stx produced neither high levels of Stx2 in vitro or lethal infection in vivo, confirming that SOS induction and concomitant expression of phage-encoded stx genes are required for disease." (PMID 30629725, 2019). "No anti Stx2 response was observed after experimental infection of calves with E. coli O157:H7." (PMID 28046078, 2017). "All the bacterial strains used in the experimental infections have been assayed for the capability to induce a cythopathic effect (CPE) onto Vero cells monolayers before infection with the stx2-phages and most of them proved negative by microscopic observation of the cell up to 72 h post inoculum." (PMID 24999453, 2014). "The eae, stx1 and stx2 genes were present in all STECs suggesting that these genes may be required for initiation of infection, but not for the development of serious disease in cattle." (PMID 24152990, 2013). "Previous reports showed that Stx2 translocation across a polarized colonic epithelial T84 cell line is enhanced by O157:H7 infection and may only occur via a transcellular pathway because TEER remains constant during infection with several STEC O157:H7 strains." (PMID 31824869, 2019).
infection (continued). "Although clear infection of S. dysenteriae type 2 (data not shown) and type 4 was observed with phages from M163 and G71 isolates, respectively but these plaques were negative in plaque blot hybridization assay with stx2 probe suggesting that isolates carrying inducible phages other than stx2 phage." (PMID 30170562, 2018). "Together with restoration of Stx2 level after vitamin B12 supplementation, these data highlight vitamin B12 as a molecule produced by gut microbiota that modulates production of a key virulence factor of EHEC and consequently may affect the outcome of an infection." (PMID 26742075, 2016). "After infection with GPU993-S, three out of six mice in the control group and four out of six treated with anti-Stx-1 IgY (200 mg/kg) died, whereas none of the six mice treated with any dose of anti-Stx-2 IgY (50, 100 and 200 mg/kg) died." (PMID 22028896, 2011).
tumor (5 papers, 2013 to 2025). "The results of IHC revealed that the STX2 protein was mainly localized to the cytomembrane and cytoplasm of the tumor cell." (PMID 29855462, 2018). "Furthermore, analysis of the GSE13507 dataset revealed that six genes, LIMS2, IRAK3, STX2, CYP27A1, IL11RA, and KCNMB1, had AUC values greater than 0.7, demonstrating good diagnostic potential in differentiating healthy adjacent tissues from tumor samples." (PMID 40755754, 2025). "To validate the expression levels of the eight key genes (LIMS2, TP53INP2, IRAK3, STX2, CYP27A1, IL11RA, KCNMB1, and PDLIM7) in tumor and non-tumor samples, we analyzed their expression in TCGA and GSE7476 datasets." (PMID 40755754, 2025). "The protein profiles of nine targets, namely IGFBP2, IGF1, SHKBP1, ETS1, IL1α, STX2, MAML3, EGR3 and XIAP were verified as significant contributors to tumor classification." (PMID 24282616, 2013). "Furthermore, qRT-PCR experiments showed that LIMS2, IRAK3, STX2, IL11RA, KCNMB1, and PDLM7 were significantly downregulated in the tumor group, consistent with the bioinformatic analysis results, suggesting their potential clinical value." (PMID 40755754, 2025).
bacterial infection (4 papers, 2014 to 2020). "Considering that macrophages are exposed to Stx2 as well as other pathogenic factors during bacterial infection, IL-1β was also tested in supernatants from macrophages infected with C600 or 125/99ΔStx2 strains." (PMID 31947665, 2020). "In this study, we found that macropinocytosis significantly contributed to Stx2 internalization only when O157:H7Δstx2 were present, indicating that bacterial infection exerts a positive effect on cell's macropinocytosis regulation." (PMID 31824869, 2019). "APC’s effects on ER stress and apoptosis transcripts were observed in both models of Stx2 toxemia, whether delivered directly by injection or by more natural daily exposure from the intestinal bacterial infection." (PMID 25609181, 2015).
cancer (4 papers, 2018 to 2025). A tumor composed of atypical neoplastic, often pleomorphic cells that invade other tissues. "STX2 participates in the tumorigenesis or metastasis of several cancers by regulating the expression of several key oncogenes, such as β-catenin and MMP99–11." (PMID 29855462, 2018). "We first assessed the sensitivity of a panel of human cancer cell lines to Stx1 and Stx2 using a 72-h cell viability assay." (PMID 30481169, 2018). "However, the findings are some contradictory with each other, which indicates that the function of STX2 in tumorigenesis and cancer development remains poorly understood." (PMID 29855462, 2018).
kidney disease (3 papers, 2010 to 2012). "Weight and age at inoculation, colon necrosis score, cecum weight, cecal colonization density, and weight loss were not correlated with aggR expression or renal ATN, suggesting that Stx2 production is most important for kidney disease development." (PMID 22848550, 2012). "More emphasis has been placed on the interaction of Stx1 and Stx2 with isolated renal cells and on kidney disease that develops in the animal models." (PMID 21297888, 2010). "What this means for D+HUS kidney disease is that it remains important not only to determine where and how much Gb3 is localized to different renal cell types, but also if the Gb3 is reactive with Stx1 or Stx2." (PMID 21297888, 2010). "Results from the mouse model of D+HUS have been instructive for kidney disease whether beginning from oral STEC or injected (i.p. or i.v.)Stx1 and Stx2." (PMID 21297888, 2010).
intestinal bacterial infection (2 papers, 2015 to 2022). "Antimicrobial-resistant E. coli and isolates with clinically relevant virulence factors such as stx1, stx2, and eae associated with human intestinal disease were rare, but stx and eae prevalence in enrichments of environmental samples was more common." (PMID 35442082, 2022).
animal diseases (1 paper, 2023). "The most severe animal diseases are caused by enterohemorrhagic (producing shiga-toxin Stx1 and/or Stx2 that stop protein synthesis in endothelial target cells) and enterotoxigenic (producing enterotoxin EAST1 and/or enterohemolisin EhxA) E. coli strains." (PMID 37628817, 2023).
gastrointestinal disease (1 paper, 2013). A disease that occurs in the gastrointestinal system, excluding the hepatobiliary system. "Shiga toxin 2 (Stx2) is a major virulence factor in gastrointestinal diseases caused by Escherichia coli." (PMID 24069462, 2013).
infectious disease (1 paper, 2022). A disorder directly resulting from the presence and activity of a microbial, viral, or parasitic agent in humans. "Effect of Stx2 on the proximal tubules seems such an important factor for STEC infectious disease; however, alterations in gene expression focusing on in vivo proximal tubular cells were not available before." (PMID 35202097, 2022).
STX2 also shares sentences with these, for which no sentence is quoted: diarrheal disease (4 papers); anemia (2); kidney (2); septicemia (2); abscess (1); acute cholecystitis (1); Arterial thrombosis (1); autism (1); cholera (1); Cognitive impairment (1); electrolyte disorders (1); enterocolitis (1); epidermoid carcinoma (1); gastrointestinal disorders (1); Hepatic fibrosis (1); Hernia (1); injury (1); kidney injury (1); lung carcinoma (1); malabsorption syndrome (1); malignant hypertension (1); microangiopathic hemolytic anemia (1); Parkinson disease (1); preeclampsia (1); pyelonephritis (1); renal dysfunction (1); thrombosis (1); urinary tract infection (1); viral infections (1); Von Willebrand disease (1).